ROPN1L (rhophilin associated tail protein 1 like)
Description:
Functions as part of axonemal radial spoke complexes that play an important part in the motility of sperm and cilia. Important for male fertility. With ROPN1, involved in fibrous sheath integrity and sperm motility, plays a role in PKA-dependent signaling processes required for spermatozoa capacitation.
Synonyms: ASP; RSPH11; FLJ25776; RP11-1C1.7; TCONS_00009352; LINC01513
Tractability: Small molecule: a structure with a bound ligand is known. Antibody: its Gene Ontology location is reachable by antibodies, with medium confidence. PROTAC: UniProt records ubiquitination sites on it; ubiquitination databases record sites on it.
Gene: Protein-coding gene on chromosome 5 (10,441,524 to 10,559,716, forward strand). Ensembl gene ENSG00000145491.
Subcellular location: Cell projection, cilium, flagellum; Cell projection, cilium
Subcellular location (Human Protein Atlas): End piece; Mid piece; Primary cilium transition zone; Principal piece; Nucleoplasm; Vesicles
Gene Ontology:
Molecular function: identical protein binding; protein binding
Biological process: cilium movement; epithelial cilium movement involved in extracellular fluid movement; flagellated sperm motility; sperm capacitation
Cellular component: ciliary transition zone; cilium; cytoplasm; motile cilium; 9+2 motile cilium; axoneme; radial spoke; sperm flagellum; extracellular region
Genetic constraint (gnomAD): Loss-of-function variants: 21 observed, 21.66 expected, observed/expected ratio (o/e) 0.97, 90% interval 0.69 to 1.4. The upper end of that interval is the gene's LOEUF score, 1.4, which puts it in group 5 of 6, group 1 being the genes least tolerant of losing a copy. Missense variants: 230 observed, 264.6 expected, observed/expected ratio (o/e) 0.87, 90% interval 0.78 to 0.97. Synonymous variants: 99 observed, 111.84 expected, observed/expected ratio (o/e) 0.89, 90% interval 0.75 to 1.05.
Homologues: Orthologues: chimpanzee ROPN1L (98% identical), macaque ROPN1L (94% identical), pig ROPN1L (80% identical), rabbit ROPN1L (78% identical), dog ROPN1L (75% identical), guinea pig ROPN1L (74% identical), mouse Ropn1l (74% identical), rat Ropn1l (74% identical), tropical clawed frog ropn1l (56% identical), zebrafish ropn1l (51% identical). Paralogues in human: ROPN1 (36% identical), ROPN1B (36% identical).
Diseases named in the same sentence as ROPN1L in open-access papers:
ROPN1L is named in the same sentence as 7 diseases in open-access papers, as found by Europe PMC text mining. Sharing a sentence is not in itself a finding about the gene and the disease. The quoted sentences say what the papers report.
breast carcinoma (2 papers, 2012 to 2021). "The 10q26.13/FGFR2 rs10736303 (proxy of rs2981579), 5p15.2/ROPN1L rs1092913, 5q12/MRPS30 rs7716600, and 8q24.21 rs1562430 were also confirmed to be associated with breast cancer risk, although the magnitude of the last three SNPs was smaller than that of previous reports." (PMID 22452962, 2012).
male infertility (2 papers, 2019 to 2022). The inability of the male to effect fertilization of an ovum after a specified period of unprotected intercourse. "Since mutations in ROPN1L affect sperm motility and can cause male infertility in mammals, it is possible that selection on this gene in Odocoileus could represent a post-mating reproductive barrier." (PMID 31684869, 2019).
cryptorchidism (1 paper, 2023). The failure of one or both testes of a male fetus to descend from the abdomen into the scrotum during the late part of pregnancy. "According to the extent of difference between cryptorchidism and normal testis, the expression of seven downregulated genes (PLCZ1, AKAP4, AKAP3, IZUMO1, SPAG6, CAPZA3, and ROPN1L) were further selected for validation by qPCR." (PMID 38027210, 2023).
ROPN1L also shares sentences with these, for which no sentence is quoted: ciliopathies (2 papers); nasopharyngeal carcinoma (1); opisthorchiasis (1); tumor (1).